IL18 (interleukin 18)
Diseases named in the same sentence as IL18 in open-access papers (continued):
Sharing a sentence is not in itself a finding about the gene and the disease.
diabetes (206 papers, 2009 to 2026). "INU and LBP interventions effectively reduced IL-18 levels, alleviating diabetes-associated inflammation, suggesting that dietary intake of INU and LBP can alleviate the inflammatory state associated with T2DM in rats." (PMID 41480362, 2025). "IL-1β and IL-18 are closely related to the occurrence and development of diabetes mellitus and are associated with metabolic homeostasis, inflammation, and IR." (PMID 41264598, 2025). "IL‐18 research is closely linked to various diseases, particularly inflammatory and autoimmune conditions like arthritis and diabetes mellitus." (PMID 39188114, 2024). "The ameliorative effect of ST on diabetes-associated inflammation was explored via the determination of hepatic IL-1β, IL-18, and TNF-α levels." (PMID 38131990, 2023). "The results showed that the expression levels of NLRP3, caspase 1, IL-1β and IL-18 were increased in CD38flox mice with diabetes compared with the normal group, whereas CD38 deficiency significantly decreased the expression of these genes at the mRNA level." (PMID 37958991, 2023). "In this study, we found that diabetes-induced vascular endothelial dysfunction was associated with increased levels of inflammatory cytokines, such as IL-1β and IL-18, which were mediated by the FTO-TNIP1-NF-κB network." (PMID 37781923, 2023). "IL-1β and IL-18 have different roles in diabetes, with IL-1β contributing to type 2 diabetes by attenuating the insulin secretion function of β-cells, and IL-18 being associated with type 1 diabetes." (PMID 36232938, 2022). "In the present study, we observed decreased differential expression of CCL4 and IL-18 at 60 days with prebiotic/probiotic supplementation, which given their associations should be associated with a reduced risk of type 2 diabetes mellitus." (PMID 36437471, 2022). "The study suggested that there are racial differences in the levels of IL-18 and the association of IL-18 with risk factors for diabetes." (PMID 34578468, 2021). "Evidence for a role in energy metabolism has been demonstrated in IL-18-deficient mice, which presented diabetes mellitus and dyslipidemia, which leads to nonalcoholic fatty liver disease and steatohepatitis." (PMID 34708129, 2021). "Lower age, male sex, greater weight and body mass index, diabetes and decreased kidney function were all associated with increased IL‐18 concentrations." (PMID 31596518, 2019). "IL-18 level has been indicated to be associated with metabolic syndrome as well as type 2 diabetes mellitus." (PMID 31525735, 2019). "We also analyzed the association between IL-18 level and other recognized ischemic stroke risk factors, including BMI, smoking, high blood pressure, diabetes, hyperlipidemia, atrial fibrillation and family history of stroke." (PMID 31525735, 2019). "The variables significantly associated with increasing IL‐18 concentration at baseline were male sex, age, diabetes, BMI > 30 kg/m2 and increasing levels of the biomarkers NT‐proBNP, cTnT‐hs, CRP‐hs, and cystatin C." (PMID 31596518, 2019). "Human studies have consistently demonstrated that higher levels of IL-18 is an independent risk factor for incident type 2 diabetes mellitus, and cardiovascular events." (PMID 30660185, 2019). "The IL‐18 levels were consistently associated with male sex, higher BMI, diabetes, decreased renal function, and to other inflammatory biomarkers." (PMID 31596518, 2019). "Higher IL‐18 levels were consistently associated with male sex, higher BMI, diabetes, decreased renal function, and other inflammatory biomarkers." (PMID 31596518, 2019). "The finding of a positive association of IL-18 with depressive symptoms in T2D is interesting, because this cytokine is also involved in the development of other diabetes-related comorbidities." (PMID 29520075, 2018). "An other study showed that in NOD mice, infiltrated macrophages in pancreatic cells expressed high levels of IL-18, which is considered to cause insulitis, a preclinical state of diabetes." (PMID 28950870, 2017).
diabetes (continued). "More recently the pro-inflammatory cytokines interleukin-15 (IL-15), interleukin-18 (IL-18) and interleukin-8 (IL-8) have been found to be more specific risk factors for coronary artery disease, diabetes and some cancers." (PMID 31011016, 2017). "In spite of the link between IL-18 promoter polymorphism, diabetes and cardiovascular disease, the relation between an IL-18 promoter polymorphism and cardiovascular disease has not been studied in diabetic nephropathy patients." (PMID 27703550, 2016). "The reduction in IL-18 levels according to the +183 G-allele was 3-4 fold more pronounced in diabetes and metabolic syndrome as compared to unaffected patients." (PMID 22141572, 2011). "Interleukin-18 was significantly associated with increased risk of diabetes in the German MONICA-KORA study, which is in agreement with our findings in FINRISK97." (PMID 20396381, 2010). "Altogether, IL-18 represents a critical node in the inflammatory network underlying diabetes." (PMID 40804870, 2025). "The presence of OLP, HCV, diabetes and hypertension is associated with higher production of IL-18." (PMID 38918874, 2024). "Reduced RBD antibodies, spike-specific B cells and follicular helper T cells were found in vaccinated participants with chronic conditions (diabetes, renal disease) and were strongly associated with altered glycosylation of IgG and increased interleukin-18 levels in the plasma." (PMID 37248417, 2023). "In several inflammatory contexts, including diabetic nephropathy, miR-146a displayed an anti-inflammatory effect, since miR-146a deficiency during diabetes led to increased expression of M1 activation markers and proinflammatory cytokines (IL1β, IL18) and suppression of M2 markers in macrophages." (PMID 37071788, 2023). "IL-18 has been shown to be involved in chronic low-grade inflammation that may be a pathogenic factor behind metabolic syndrome and type 2 diabetes mellitus." (PMID 37175211, 2023). "IL-18 has been implicated in the expansion of islet-destructive T-cells during pre-diabetes." (PMID 36313762, 2022). "Data from a meta-analysis reveals that T2DM (type 2 diabetes mellitus) risk as a whole was solidly correlated with increased levels of inflammatory cytokines such as interleukin (IL) 1β, IL-6, IL-18, C reactive protein (CRP) and tumor necrosis factor-α (TNF-α)." (PMID 34829612, 2021). "In addition, Genotype A/A of IL-18 gene promoter -607 C/A polymorphism was related to the prevalence of type 2 diabetes mellitus and the level of blood glucose after 2 h." (PMID 31835423, 2019). "A deficiency in IL-18 resulted in kidney injury in younger mice but protection from renal damage was observed in mice aged 48 weeks even though Il18−/− mice showed signs of diabetes mellitus, dyslipidemia, and arteriosclerosis." (PMID 29514661, 2018). "It has been reported that IL-18 levels are associated with the evolution of diabetes." (PMID 28950870, 2017). "IL-18 has also been implicated in the evolution of diabetes." (PMID 28950870, 2017). "Additionally, diabetes is associated with high levels of blood cytokines including IL-1β, IL-6, IL-12, IL-17, IL-18, TNF-α and IFN-γ, which mediate the physiological adaption of insulin production and insulin resistance." (PMID 26684748, 2015). "Previously, we have shown that TSA treatment alleviated T1D in NOD mice and also up-regulated the expression of the transcription factor Tbx21/Tbet and Ifng genes without altering the levels of some of the genes implicated in diabetes such as Il4, Il17, Il18, and Tnfa in activated T lymphocytes." (PMID 23383062, 2013). "Therefore, we suggest that β-NGF can be helpful as index of that chronic infection stage able to evolve into cirrhosis and, then, HCC while glucagon and IL-18 can be index of the diabetes association that occurs as part of the metabolic syndrome leading to HCC." (PMID 22745767, 2012).
diabetes (continued). "Future studies are warranted to explore IL-18-targeted therapies as potential strategies to mitigate both the immunologic and metabolic burden of diabetes." (PMID 40804870, 2025). "Some animal studies have shown that blocking IL-18 can help to reduce the autoimmune response and prevent or delay the onset of diabetes." (PMID 40277935, 2025). "Previous studies have demonstrated that both INU and LBP can elevate interleukin-18 (IL-18) levels in individuals with diabetes mellitus." (PMID 41480362, 2025). "Beyond autoimmunity, IL-18 plays a central role in the progression of diabetes-related complications, especially diabetic nephropathy." (PMID 40804870, 2025). "In the current study, we found that diabetes impaired macrophage lipid metabolism during liver IR and caused more severe aseptic inflammation (TNF‐α, IL‐1β, IL‐6, and IL‐18)." (PMID 40778489, 2025). "Taken together, IL-8/CXCL8 and IL-18 appear related with depressive symptoms irrespectively of diabetes status." (PMID 39799156, 2025). "Surprisingly, elevated IL‐18 didn't significantly correlate with adverse events in patients with diabetes, higher Gensini scores, or diagnosed with UA, likely due to smaller subgroup sizes." (PMID 38402570, 2024). "Significantly high levels of IL-18 were found among patients with diabetes, hypertension (p < 0.01 in both)." (PMID 38918874, 2024). "In diabetic nephropathy, serum IL-18 levels are elevated and can be a predictive biomarker for the initiation of diabetic nephropathy in patients with diabetes." (PMID 38328001, 2024). "It has been reported that miR-9-5p can mitigate diabetes by downregulating pyroptosis, which is coupled with reductions in IL-1β, IL-18, NLRP3, and Caspase-1." (PMID 38934781, 2024). "While IL‐1β promotes insulin resistance and diabetes, IL‐18 regulates energy expenditure and food intake." (PMID 38629728, 2024). "It activates the inactive forms of pro-inflammatory cytokines IL-1β and IL-18, the over expression of these cytokines promotes several diseases including diabetes mellitus." (PMID 36653816, 2023). "In diabetes, an elevated level of IL-18 was reported, and this cytokine is also used to predict the risk of cardiovascular diseases." (PMID 37457235, 2023). "In this experiment the upregulation of IL‐18 has been shown, which is in line with several studies showing IL-18 elevation and upregulation in diabetes patients." (PMID 37457235, 2023). "There were lower levels of all inflammatory parameters in the presence of diabetes, and this was found to be statistically significant for IL-18 and hsCRP in the MID group (p = 0.035 and p = 0.021, respectively)." (PMID 37763063, 2023). "A more significant IL-18 decrease was noted among patients with diabetes (n = 12, p = 0.003) receiving tandem therapy (p = 0.013)." (PMID 37108668, 2023). "IL-18 concentration decrease was more significant in patients with diabetes (p = 0.003), and those treated with [177Lu]Lu-DOTATATE/[90Y]Y (p = 0.013)." (PMID 36615845, 2022). "NLRP3 inflammasome, IL-1β, and IL-18 can affect blood glucose control and insulin resistance, which are related to the pathogenesis of diabetes, and play an important role in diabetes-induced systemic chronic inflammation and insulin signal transduction." (PMID 36248820, 2022). "Tai Chi intervention can reduce blood glucose, blood lipid, and insulin resistance levels and decrease the serum levels of inflammatory factors, including NF-κB, ROS, NLRP3, IL-1β, and IL-18 in pre-diabetes." (PMID 36248820, 2022). "It is activated under diabetes conditions that promotes caspase-1 autocleavage, and the maturation of pro-IL-1β/18, IL-1β, and IL-18 is secreted into the extracellular space to participate in the subsequent inflammatory response." (PMID 36111168, 2022). "The administration of IL-18 via IL-18 expressing plasmid delivery to 4 weeks old NOD mice promoted the development of insulitis/diabetes." (PMID 36032110, 2022).
diabetes (continued). "In patients with diabetes, the expression of IL-18, an inflammatory cytokine released during pyroptosis in renal tubular cells, increases significantly (approximately 83%), suggesting the potential involvement of pyroptosis in RTEC damage." (PMID 36204129, 2022). "IL-1β and IL-18 are two essential pro-inflammatory cytokines that are upregulated in tissue-resident cells of patients and animals with diabetes and are further induced by positive feedback to pyroptosis to form inflammatory storms." (PMID 36204129, 2022). "Mediators of inflammation—TNF-α, IL-1β, the IL-6 family of cytokines, IL-18, and certain chemokines—are believed to be involved in the etiology of diabetes." (PMID 35330193, 2022). "Collectively, it suggests that IL-18 plays a role in glucose homeostasis, insulin secretion, and the development of diabetes." (PMID 36547931, 2022). "Elevated CCL4 and IL-18 result in elevated systemic inflammation and the onset and progression of type 2 diabetes mellitus." (PMID 36437471, 2022). "Those authors presented for the first time that IL-18 cytokine plays a crucial role in the development of murine diabetes when STZ is applied." (PMID 34944607, 2021). "Under “diabetes-like” conditions, WT HspB4/αA-crystallin overexpression led to the significant reduction of the induction of IL-6 (55%), IL-1β (36%), IL-18 (93%), and MCP-1 (85%) by MGCs (HspB4−/−)." (PMID 34071438, 2021). "In the present study, in diabetes patients, IL-18 was higher in value both pre- and post-extraction when compared to systemically healthy patients, which confirms the increased inflammatory load for these individuals." (PMID 34829612, 2021). "Both IL-1β and IL-18 cytokines increase with progression to diabetes and destruction of the islet β-cells." (PMID 34177937, 2021). "AD reduced hyperglycemia, inhibited the development of oxidative stress, and was able to retard inflammation and apoptosis in diabetes by blocking the production of IL-18 and caspase 3 via the deregulation of NFkB expressions in the treated diabetic rats." (PMID 32046294, 2020). "The insignificance of IL-18 for the development of metabolic syndrome is in line with a study in humans where an anti-IL-18 monoclonal antibody was ineffective for the treatment of type 2 diabetes mellitus." (PMID 33202693, 2020). "We also demonstrated that NLRP3 inflammasome activation by mitochondrial DNA promotes IL-1β and IL-18 release, contributing to the generation of pathogenic Th17/Th1 cells in the PLNs and increasing T1D susceptibility in STZ-induced diabetes." (PMID 32295112, 2020). "First, MFG-E8 is an endogenous inhibitor of NLRP3 inflammasome-induced IL-1β/IL-18 production in wound site of diabetes." (PMID 32963812, 2020). "For example, black race, current smoking, diabetes, HCV-seropositivity, and higher HIV viral load were individually associated with higher levels of IL-18, whereas higher CD4+ count was associated with lower IL-18 levels." (PMID 30606136, 2019). "The results showed that IL-18 level in IGR or type 2 diabetes mellitus was remarkably increased in comparison that in normal glucose regulation." (PMID 31835423, 2019). "When evaluating urinary secretion of inflammatory cytokines in rats with diabetes, the use of the antagonist greatly decreased the levels of the cytokines IL-1β and IL18, which were increased by diabetes." (PMID 31540220, 2019). "What is more, the authors of this study noticed, that IL-18 level differs in time after diabetes induction." (PMID 31771099, 2019). "IL-1β and IL-18 are two interleukins from the cytokine lists that are believed to play important roles in the pathogenesis of diabetes." (PMID 30704457, 2019). "With regard to this cytokine, we demonstrated that maternal diabetes diminished the expression of il-18 in the offspring hippocampi (p < 0.05)." (PMID 31197747, 2019).
diabetes (continued). "In human studies, the serum concentration of IL-18 was found to be significantly higher in patients with metabolic syndrome, type 2 diabetes mellitus, or diabetic nephropathy compared with healthy control participants." (PMID 29514661, 2018). "A previous study found that Il18−/− mice showed severe insulin resistance resulting in diabetes mellitus; however, specific renal complications remain uncertain." (PMID 29514661, 2018). "In human studies, the serum concentration of IL-18 was significantly higher in patients with type 2 diabetes mellitus and with metabolic syndrome than in healthy controls." (PMID 30453990, 2018). "Il18−/− mice show dyslipidemia at 6 weeks old, develop diabetes mellitus, and show high glucose and insulin levels and arteriosclerosis at 6 months old, and NAFLD or NASH at 48 weeks old." (PMID 29514661, 2018). "In age and sex adjusted Cox models, IL13 (HR = 0.78), EN-RAGE (1.30), CFH (1.24), IL18 (1.22) and CRP (1.32) were associated with incident pre-diabetes." (PMID 28258520, 2017). "The mortality of PD patients was increased while they had increasing numbers of predictive factors including titers of IL-18 ≧ 804.3 pg/ml, titers of IL-6 ≧ 3.92 pg/ml, titers of IL-1ß ≧ 0.86 pg/ml, age ≧ 50 years-old, and diabetes." (PMID 28474577, 2017). "Activation of the NLRP3 inflammasome promotes renal injury through the up-regulation of IL-1β and IL-18, and enhances IL-1β production in diabetes." (PMID 28708885, 2017). "In age and sex adjusted model, EN-RAGE, IL13, CFH, IL18 and CRP were associated with incident pre-diabetes." (PMID 28258520, 2017). "Diabetes mellitus, age ≧ 50 years, IL-18 ≧ 804.3 pg/ml, IL-6 ≧ 3.92 pg/ml, IL-1ß ≧ 0.86 pg/ml, and average levels of albumin <3.8 gm/dl." (PMID 28474577, 2017). "existence of diabetes mellitus, age 2: 50 years, IL-18 2 804.3 pg/ml, IL-6 2 3.92 pg/ml, and IL-1B 2 0.86 pg/ml." (PMID 28474577, 2017). "Definition of factors, existence of diabetes mellitus, age 2 50 years, IL-18 2 804.3 pg/ml, IL-6 2 3.92 pg/ml, IL-1B 2 0.86 pg/ml, and averaging albumin level < 3.8 gm/dl within the first year of PD." (PMID 28474577, 2017). "We observed no influence of cigarette smoking and comorbidities such as IHD, hypertension, or diabetes on serum IL-18, fetuin-A, sICAM-1, and ET-1 levels in SpA patients." (PMID 27527149, 2016). "In agreement we also found that diabetes associated increase in renal cortical TGF beta, RAGE, IL-6, IL-18, matrix metalloproteases (MMPs, MMP2 and 9) mRNA expression were prevented in treated groups." (PMID 27901066, 2016). "Urinary and serum levels of IL-6 and IL-18 mRNA were significantly elevated but those of TTP were significantly decreased in diabetes patients compared with healthy controls (P<0.001)." (PMID 26517838, 2015). "It has therefore been suggested that there is a plausible correlation between the functions of IL-18 and type 1 diabetes mellitus (T1DM), T2DM, obesity, and CVD." (PMID 24282409, 2013). "This study describes novel observations regarding the differences in acute inflammatory responses of IL-6, IL-10, and IL-18 for severely obese patients with type 2 diabetes mellitus (DM) from the responses of lean patients." (PMID 24555158, 2013). "Prospective studies evaluating the effect of elevated circulating IL-18 levels on cardiovascular, metabolic syndrome and diabetes related end points." (PMID 20331890, 2010). "However, a major limitation of both studies is that fasting glucose or oral glucose tolerance tests were not performed at baseline evaluation: Elevated fasting glucose increases the risk of diabetes, and experimental hyperglycemia might increase circulating levels of IL-18." (PMID 20331890, 2010). "Circulating levels of IL-18 have consistently been reported to be elevated in patients with type 2 diabetes mellitus in cross sectional studies, and have also been suggested to contribute to microangiopathy such as nephropathy in type 2 diabetes." (PMID 20331890, 2010).